KLK12 (kallikrein related peptidase 12)
Synonyms: KLK-L5; KLKL5
Tractability: Antibody: its Gene Ontology location is reachable by antibodies, with high confidence; UniProt places it where antibodies can reach, with medium confidence; UniProt predicts a signal peptide or a membrane-spanning region.
Target class: Serine protease; Enzyme; Serine protease PA clan; Serine protease S1A subfamily; Protease
Gene: Protein-coding gene on chromosome 19 (51,029,092 to 51,035,230, reverse strand). Ensembl gene ENSG00000186474.
Subcellular location: Secreted
Pathways (Reactome):
Developmental Biology: Formation of the cornified envelope
Gene Ontology:
Molecular function: peptidase activity; serine-type peptidase activity; serine-type endopeptidase activity
Biological process: proteolysis; protein maturation
Cellular component: extracellular region; secretory granule
Genetic constraint (gnomAD): Loss-of-function variants: 23 observed, 20.9 expected, observed/expected ratio (o/e) 1.1, 90% interval 0.79 to 1.56. The upper end of that interval is the gene's LOEUF score, 1.56, which puts it in group 6 of 6, group 1 being the genes least tolerant of losing a copy. Missense variants: 351 observed, 338.44 expected, observed/expected ratio (o/e) 1.04, 90% interval 0.95 to 1.13. Synonymous variants: 147 observed, 141.81 expected, observed/expected ratio (o/e) 1.04, 90% interval 0.91 to 1.19.
Homologues: Orthologues: chimpanzee KLK12 (94% identical), pig KLK12 (79% identical), macaque KLK12 (76% identical), dog KLK12 (74% identical), rat Klk12 (71% identical), mouse Klk12 (70% identical), tropical clawed frog klk1 (39% identical), Drosophila melanogaster CG32808 (29% identical), Drosophila melanogaster CG31269 (28% identical), Drosophila melanogaster Send2 (28% identical), Drosophila melanogaster CG3916 (26% identical), Drosophila melanogaster CG12256 (25% identical), and 6 more. Paralogues in human: KLK8 (48% identical), KLK11 (48% identical), KLK14 (46% identical), KLK7 (45% identical), KLK5 (44% identical), KLK2 (41% identical), KLK1 (40% identical), KLK3 (40% identical), KLK4 (40% identical), TMPRSS4 (31% identical), PRSS58 (30% identical), PRSS54 (21% identical).